ALB (albumin)
Diseases named in the same sentence as ALB in open-access papers (continued):
Sharing a sentence is not in itself a finding about the gene and the disease.
diabetes (continued). "After adjustment, age, diabetes mellitus and predialysis hyperkalemia with a serum potassium concentration >5.0 mEq/L were independent adverse predictors, and exposure to 1.0 mEq/L potassium dialysate, Kt/V, and serum albumin remained as independent protective predictors of all-cause mortality." (PMID 26440515, 2015). "However, adjusting for specific gravity may bias associations with diabetes because urine of diabetic individuals, compared with healthy subjects, contains higher levels of albumin and glucose, resulting in higher specific gravity." (PMID 25000461, 2014). "In fact, albumin not only increases the relaxivity of gadolinium complexes in the blood pool, but also emerges as a versatile carrier for a long list of therapeutic and diagnostic agents in pathologies such as diabetes, cancer, rheumatoid arthritis and infectious diseases." (PMID 23067266, 2012). "Our results clearly demonstrate that patients with more signs of inflammation andlower albumin levels face an increased risk of all-cause mortality.Furthermore, comparison between survivors and deceased patients found that deceased patientswere older and more likely to have diabetes." (PMID 18288267, 2007). "These 12 variables included sex, education level, marital status, diabetes, hypertension, smoking status, BMI, daily energy intake, albumin, platelet count, MLR, and NMLR." (PMID 41607949, 2026). "HbA1c, weekly frequency of SMBG, hospitalisations, waist circumference, blood pressure, lipid levels, albumin secretion and diabetes distress." (PMID 41277464, 2026). "All results remained after adjustment for age, sex, log2 time since transplantation, polypharmacy, diabetes, anemia, hemoglobin level, eGFR, albumin level, log2 NT-proBNP level, tacrolimus use, cyclosporine use, predniso(lo)ne use, and PPI use (model 1)." (PMID 41503188, 2026). "Other variables related to Gensini scores included age, gender, smoking, diabetes, hypertension, eGFR, urinary albumin, phosphate, LDL-cholesterol, hemoglobin, hsCRP, and intact PTH." (PMID 41597410, 2026). "Older age, women, and diabetes were associated with increased odds of having ASB, whereas high physical activity and serum albumin levels were associated with decreased odds." (PMID 41843590, 2026). "LASSO regression identified three independent predictors: diabetes (OR: 2.451; 95% CI: 1.139-5.274), maximum norepinephrine dose (OR: 2.051; 95% CI: 1.322-3.182), and albumin level at ICU admission (OR: 0.834 per unit increase; 95% CI: 0.776-0.897)." (PMID 42232962, 2026). "Our study showed a strong association between the patients′ length of diabetes and higher HbA1c, CRP, and urine albumin levels, as well as the prevalence of DR." (PMID 41541002, 2026). "DKD was defined as reduced eGFR or increased urinary albumin-to-creatinine ratio in individuals with diabetes." (PMID 41659341, 2026). "We performed multivariable binary logistic regression analyses to assess the independent associations between systemic inflammatory indices and the presence of DFU, adjusting for age, sex, diabetes duration, BMI, and albumin levels." (PMID 41728362, 2026). "Multivariate analysis showed that age, diabetes mellitus, prealbumin before feeding, albumin before feeding, parenteral nutrition support and rapid enteral feeding were independent risk factors (P< 0.05)." (PMID 41939463, 2026). "For differential diagnosis, the random forest (RF) model achieved an AUC of 0.901, with diabetic retinopathy, diabetes duration, albumin, blood urea nitrogen, MR2*, hypertension, and glycosylated hemoglobin as the most contributing factors." (PMID 42008071, 2026). "GDF15 values statistically correlated with age, prevalence of diabetes, serum level of aspartate aminotransferase/γ-glutamyltransferase/creatinine/blood sugar/albumin, and PMI." (PMID 41016991, 2026). "Our study revealed a significant association between the prevalence of DR and diabetes duration, HbA1c, CRP, and urinary albumin levels." (PMID 41541002, 2026).
diabetes (continued). "Our research has shown a significant association between the prevalence of DR and elevated levels of HbA1c, CRP, and urinary albumin and duration of diabetes." (PMID 41541002, 2026). "The association between serum C3 levels and renal injury was evaluated using multivariable linear regression and binary logistic regression analyses, after adjusting for age, sex, TC, duration of diabetes, HbA1c, albumin and 24-h (24-hour) proteinuria." (PMID 42064082, 2026). "Baseline characteristics such as race, marital status, education level, smoking and drinking status, diabetes, hypertension, energy intake, and albumin showed significant statistical differences among different OA statuses." (PMID 41607949, 2026). "Diabetes duration was ≥ 10 years in 62%, 41% received insulin treatment before infection, 80% had HbA1c ≥ 7%, 12% had albumin < 2.5 g/dL, and 75% had hemoglobin < 8 g/dL." (PMID 41564031, 2026). "The primary factors influencing frailty encompass gender, age, obesity, low income, marital status, physical dysfunction, peripheral vascular disease, heart disease, diabetes, albumin levels, sarcopenia, cognitive impairment, and depression." (PMID 41601521, 2026). "The p values of data being 0.000, 0.000, 0003, and 0.002 when the relationship between diabetes duration/HbA1c/urine albumin/CRP levels and the prevalence of diabetes were assessed, respectively." (PMID 41541002, 2026). "Univariate Cox regression analysis identified age, comorbid diabetes and CHD, use of lipid-regulating agents, higher levels of Hb, NLR, PLR, GLR, and SCr/CysC, along with lower levels of LMR and ALB, as risk factors for all-cause mortality (all p < 0.05)." (PMID 41280395, 2025). "Our longitudinal cohort study was aimed at addressing these gaps by systematically evaluating 5-year trajectories of both eGFR and urinary albumin excretion rate (AER) in adults with Type 2 diabetes mellitus (T2DM)." (PMID 40860624, 2025). "Guidelines recommend routine urine albumin-to-creatinine ratio (uACR) screening in patients with diabetes (annual) and hypertension (at least once, with follow-up annually if CKD is found)." (PMID 41345917, 2025). "We then included relevant covariates in an adjusted model, which were: age, male sex, ischemic heart disease, diabetes, hypertension, systolic blood pressure, heart rate, serum hemoglobin, creatinine, albumin, NT-proBNP, and left atrial volume index." (PMID 40665910, 2025). "In people with type 1 diabetes, kidney damage, a common consequence of diabetes, is detected by a urine albumin-to-creatinine ratio (ACR) test." (PMID 41361288, 2025). "It resulted in a significant association between all-cause mortality and older age, male gender, more severe carotidal VC, increased CRP, low albumin, presence of diabetes, and cardiovascular diseases." (PMID 40136613, 2025). "The groups differed significantly in serum albumin levels, rates of previous abdominal surgery, diabetes mellitus, hypertension, laparoscopic surgery, tumor location, and estimated blood loss." (PMID 40046519, 2025). "Model 1 = adjusted for age, sex, schooling, hypertension, diabetes, cardiovascular disease, stroke, smoke, alcohol, physical activity, cognitive performance, and BMI; Model 2 = Model 1 + C-reactive protein and albumin." (PMID 40929405, 2025). "These included duration of diabetes (p=0.0369), systolic blood pressure (p<0.0001), serum creatinine (p<0.0001), urine protein (p=0.0224), urine total protein (p=0.0129), and urine albumin/Cr (p<0.0001)." (PMID 40822949, 2025). "Participants with coronary artery disease, stroke, liver disease, renal failure, hyperuricemia, gout, diabetes mellitus, or taking medications that affect albumin or uric acid levels were excluded." (PMID 39897307, 2025). "Single nutritional measures, such as serum albumin (ALB), have been shown to play an important role in predicting nutritional status and outcomes in patients with chronic diseases (e.g., diabetes, hypertension, and COPD)." (PMID 40469675, 2025).
diabetes (continued). "The most common predictors include duration of diabetes, age, glycosylated hemoglobin, serum creatinine and urinary albumin creatinine ratio." (PMID 40717809, 2025). "Models were adjusted for age, sex, diabetes, BMI, smoking status, estimated glomerular filtration rate, serum albumin, CRP, calcium, phosphate, and statin use." (PMID 40786290, 2025). "Across higher categories of uACR, patients were younger, more often men, had a higher prevalence of hypertension, diabetes and acute kidney injury, had lower eGFR and serum albumin level, and were prescribed RASi less often." (PMID 38688876, 2025). "There was no statistical difference in T2 after further adjustment for smoking, alcohol intake, hypertension, diabetes mellitus, and albumin levels (g/dL) in Model 3, whereas, the ORs of T3 were 0.69 (95%CI, 0.56–0.85, P for tend = 0.001)." (PMID 40600153, 2025). "We found that age, diabetes mellitus, bilateral renal vein thrombosis, malignancy, sepsis, serum albumin, and low hemoglobin levels at diagnosis were predictors of all-cause mortality." (PMID 39739269, 2025). "Firstly, the research identified independent risk factors associated with GIB, including gender, Sequential Organ Failure Assessment (SOFA) score, shock index (SI), blood urea nitrogen (BUN), albumin levels, and diabetes." (PMID 40297154, 2025). "Baseline characteristics according to glycated albumin‐to‐glycated haemoglobin ratio categorised as tertiles in participants with diabetes." (PMID 40590067, 2025). "The basic model was developed according to age, race, marital status, education level, PIR, smoking history, alcohol consumption, age at menopause, BMI, diabetes, albumin, AST, ALT, LDL-c, SUA, and eGFR." (PMID 40810068, 2025). "Other promising developments include albumin–insulin conjugates for diabetes management, which leverage albumin’s prolonged half-life to achieve sustained glucose control, as well as albumin-bound photosensitizers for photodynamic cancer therapy." (PMID 40699702, 2025). "Component analysis of the NAFLD Fibrosis Score (NFS) revealed that metabolic factors, BMI, and diabetes accounted for 72% of its variance, whereas fibrosis-specific markers, such as albumin, contributed only 14%." (PMID 40954485, 2025). "Across a total of 17 studies, 7 factors including age, D-dimer, C-reactive protein, sequential organ failure assessment (SOFA) score, body temperature, albumin, and diabetes have the highest consistency as predictors of COVID-19 severity." (PMID 40218195, 2025). "The risk factors include Age, BMI, Pathological staging, Hemoglobin, Lymphocyte, Diabetes, Liver function, History of radiotherapy, Chemotherapy regimen, Genetic factors, and Albumin." (PMID 41438123, 2025). "Examination of the relative content of AGEs and DT has shown higher levels of both modifications in albumin isolated from persons with diabetes than from healthy individuals." (PMID 41321387, 2025). "Cachexia was significantly associated with older age, higher ASA score, elevated CEA levels, decreased albumin, chronic pulmonary disease, diabetes mellitus, BMI, reduced VFA and SFA, and higher tumor, node, and TNM stages." (PMID 40098734, 2025). "Diabetes, advanced disease, ASA score, low hemoglobin, serum albumin, operative time, and blood loss were significant predictors, corroborating prior findings." (PMID 41280976, 2025). "Low serum albumin level, proteinuria and poor diabetes mellitus control were factors to exacerbate renal function after TACE." (PMID 39739853, 2025). "The different participants showed significant differences (p < 0.001) in variables, such as age; sex; education level; serum AST, ALT, and ALB levels; prevalence of hypertension; diabetes; and physical activity patterns." (PMID 40241906, 2025). "Key variables selected for matching included BMI, diabetes duration, serum albumin, triglyceride, and the presence of cardiovascular disease." (PMID 40123891, 2025).
diabetes (continued). "Carotid VC, diabetes, low serum albumin, high serum C-reactive protein (CRP), and the presence of cardiovascular diseases are associated with all-cause and cardiovascular mortality." (PMID 40136613, 2025). "In rats with STZ-induced diabetes that were fed a high-fat diet, the isoflavonoid formononetin reduced the high circulating concentrations of creatinine, urea nitrogen, and albumin." (PMID 41020857, 2025). "The most frequent variables used for covariate adjustment were age, blood pressure or hypertension, eGFR, serum protein or albumin, baseline proteinuria, gender, diabetes and BMI." (PMID 41573529, 2025). "In our study, patients with lower albumin levels were more likely to have comorbidities such as anemia, heart disease, hypertension, diabetes, stroke, renal disease, liver disease, and COPD." (PMID 41200138, 2025). "Among the 154 individuals with diabetes in the pre‐dialysis cohort, 93.4% had albumin‐to‐creatinine ratio (ACR) assessments within the past year." (PMID 38859547, 2025). "Overall, our findings corroborate previous research regarding the high incidence of OH in MHD patients and elucidate the critical roles of advanced age, diabetes, and low serum ALB in its pathogenesis." (PMID 41281282, 2025). "Feature selection identified six risk factors—gender, SOFA score, shock index (SI), blood urea nitrogen (BUN), albumin level, and diabetes status—as important predictors of GIB in ICU-admitted TBI patients." (PMID 40297154, 2025). "Eight independent predictors of PU were identified: diabetes duration, BMI, albumin, prealbumin, age, hemoglobin, temperature difference, and urinary incontinence." (PMID 40672825, 2025). "In a sensitivity model that additionally included age, diabetes, and albumin, muscle density, muscle volume, hypertension, and ApoB remained significant variables associated with CVEs, whereas HbA1c lost significance." (PMID 41299285, 2025). "DKD is diagnosed in patients with diabetes either by renal biopsy or clinically by an albumin/creatinine ratio (ACR) ≥ 30 mg/g and/or sustained reduction in estimated glomerular filtration rate (eGFR) ≤ 60 mL/min per 1.73 m2." (PMID 39934556, 2025). "All the variables with p < 0.05 in univariate models, including hypotension, diabetes, dyslipidemia, albumin, PhA, SMI, FFM, TBW, and ECW/TBW, were considered and included when conducting the multivariate regression analysis." (PMID 40995176, 2025). "Other significant risk factors for all-cause and cardiovascular mortality were diabetes, high CRP, and low albumin." (PMID 40136613, 2025). "In cases of prolonged conservative treatment, several independent risk factors were identified, including median age (62.5 years vs. 67 years), albumin and total protein levels, and the presence of diabetes mellitus." (PMID 40095815, 2025). "In conclusion, the primary independent risk factors for TISVAP-related infections include a history of diabetes, the type of chemotherapy, leukocyte levels, and serum albumin concentrations." (PMID 39773012, 2025). "Serum albumin, the most abundant plasma protein, can be influenced by factors such as nutrition, liver dysfunction, malignancy, stress, and comorbidities (e.g., diabetes), and its level serves as an indicator of nutritional status." (PMID 41200138, 2025). "Of the participants with diabetes, 27 had normal urinary albumin-to-creatinine ratio (stage A1), 14 had microalbuminuria (stage A2), and 8 had macroalbuminuria (stage A3)." (PMID 39782685, 2025). "For example, when patients with diabetes drank green tea containing 800 mg of epigallocatechin gallate daily for 12 weeks, their urinary albumin-to-creatinine ratio decreased by 41%, implying that it had a renoprotective effect." (PMID 41020857, 2025). "ROC curve analysis identified a Glycated Albumin cutoff of 14.95% for Diabetes Mellitus diagnosis, with a sensitivity of 93.1% and specificity of 89.1%." (PMID 40924301, 2025).
diabetes (continued). "The model is based on independent risk factors identified in our study: a history of diabetes, the type of chemotherapy, peripheral blood leukocyte count (WBC), and serum albumin levels." (PMID 39773012, 2025). "Correlation factors for AL after esophageal cancer surgery have been reported to include BMI, tumor location, albumin level, and comorbidities such as diabetes mellitus and COPD." (PMID 40108066, 2025). "The result of univariate analysis indicated that sex, age, diabetes duration, smoking, lymphocyte, PLR, MLR, NLR, ALT, AST, total protein, albumin, FPG, FCP, eGFR, BMI, TBW, ICW, and ECW were associated with DPN." (PMID 41180191, 2025). "Third, due to time constraints we were unable to collect detailed clinical information, such as diabetes status, hemoglobin levels, and albumin levels, which have been shown in previous studies to be associated with QoL." (PMID 40740281, 2025). "Among 300 patients (mean age 67 ± 13 years; 73% male), 39% had diabetes, mean estimated glomerular filtration rate was 63 ± 18 ml/min/1.73 m2, median urine albumin-to-creatinine ratio was 34 mg/g (13–84 mg/g), and 58% had CKD." (PMID 40121450, 2025). "Highly prevalent diseases such as hypertension (HTN) and diabetes mellitus (DM) are highly related to the development of renal damage, characterised by increases in urinary albumin excretion (UAE) and/or a decrease in the glomerular filtration rate (GFR)." (PMID 40723868, 2025). "In contrast, higher body mass index, Kt/Vurea, hemoglobin, albumin, and transferrin saturation rate, along with statin use and the presence of CVA or diabetes, tended to be associated with lower ERI quartiles." (PMID 40283642, 2025). "The combined analysis of C-reactive protein, serum WBC count, and albumin test results, can provide an early identification basis for sepsis in patients with diabetes complicated with UTIs." (PMID 40510484, 2025). "Those in the highest quartile exhibited lower levels of FPG, HbA1c, ALT, TG, SUA, and SCr, a lower prevalence of diabetes and hypertension, and higher levels of albumin, TC, HDL-c, LDL-c, eGFR, and eGDR compared to the first quartile (P<0.001)." (PMID 40810068, 2025). "In our study, low albumin/hemoglobin and unstable blood glucose in diabetes patients were corrected during the perioperative period." (PMID 40142662, 2025). "Urinary albumin testing in Japan is only accepted for reimbursement in diabetes mellitus or early diabetic nephropathy." (PMID 40839334, 2025). "Serum albumin emerged as a key independent correlate (β = -0.543, p < 0.001), holding steady after corrections for age, gender, hypertension, and diabetes." (PMID 41536368, 2025). "Reducing tubular workload and mitigating hypoxia in the proximal tubule as a result of hyperglycemia and glomerular hyperfiltration in patients with diabetes through glucose excretion and reductions in urinary albumin excretion." (PMID 41431542, 2025). "Cases of diabetes with nephropathy, i.e., overt proteinuria, microalbuminuria on urinalysis (albumin level higher than 30 mg/24 h), or renal impairment." (PMID 40581959, 2025). "Before PSM, there were significant differences between the 2 groups in terms of age, stroke type, NIHSS score, GCS score, presence of hypertension, diabetes, serum albumin level, time to initiation of EN, APACHE II score, and SOFA score (P < .05)." (PMID 41261691, 2025). "According to the results of Bayesian network model, lower albumin levels and diabetes were more common in patients with higher age than in those with lower age." (PMID 40837566, 2025). "After adjusting for sex, significant differences persisted in age, diabetes duration, follow-up time, and albumin levels." (PMID 40860624, 2025). "The incidence of chronic diseases (such as hypertension and diabetes) was increased among COVID-19 patients with decreased serum albumin." (PMID 41574293, 2025).